IL15 (interleukin 15)
Diseases named in the same sentence as IL15 in open-access papers (continued):
Sharing a sentence is not in itself a finding about the gene and the disease.
leukemia (continued). "In this study we compared the effects of IL-15sol vs IL-15Rc in their role as immunomodulators in the 70Z/3-L leukemia mouse model in order to evaluate the potential of IL-15 as an immunotherapeutic." (PMID 31856922, 2019). "While the role for IL-15 in leukemia proliferation and survival is discussed in the next section, IL-15 also upregulates p-selectin glycoprotein ligand-1 (PSGL-1) and CXCR3 levels in leukemia cells." (PMID 28491865, 2017). "In contrast, thymic naïve γδ T cells secrete IFN-γ in the presence of IL-2 or IL-15, through the de novo expression of T-bet and eomesodermin, and the release of cytotoxic molecules against leukemia cells." (PMID 28713381, 2017). "We first use our attractor-finding method on the T-LGL leukemia network in the presence of the external signals Stimuli and IL15 to obtain the stable motifs and the succession diagram." (PMID 25849586, 2015). "Most importantly, we demonstrate that a single UCB-NK cell infusion combined with supportive IL-15 administration efficiently inhibited growth of human leukemia cells implanted in the femur of mice, resulting in significant prolongation of mice survival." (PMID 23755121, 2013). "In terms of promoting the proliferation of cancer cells, IL15 binds to receptors on the cell surface, leading to the activation of a series of intracellular signaling pathways and resulting in the proliferation of leukemia cells." (PMID 40070829, 2025). "A mouse model revealed that melding NK cells with exogenous IL-15 could boost immune effector cells to eliminate leukemia following allogeneic HSCT." (PMID 39411712, 2024). "Besides direct action on AML cells, indirect effects of FLT3 inhibitors, such as weakened expression of PD-1 and TIGIT within donor CD8+ T cells and increased production of IL-15, enhance the graft-versus-leukemia effect." (PMID 39273395, 2024). "However, the potential of using IL-15 to mobilize substantial effector populations against AML and induce graft-versus-leukemia responses is hindered due to toxicity associated with IL-15 infusion." (PMID 39273395, 2024). "We also evaluated the impact of the Scid mutation on leukemia development in the C57BL/6 genetic background to rule out the possibility that leukemia development in IL-15-deficient Scid mice is dependent on NOD genetic background." (PMID 36765626, 2023). "Interestingly, we have identified the IL-15 production pathway to be activated in leukemia cells cultured in the 3D BM niche-like AML model, with different associated genes upregulated, including EGFR, IGF1R, MET, RELB, and ERBB2." (PMID 37932837, 2023). "Numerous IL-15-enhancing approaches have been used to treat different cancers, including leukemias and lymphomas, exploiting the main function of the cytokine to potentiate Natural Killer (NK) and T-cell responses and unleash immune-mediated cancer eradication." (PMID 37153603, 2023). "In addition, coculture with the leukemia cell line K562 overexpressing 4‐1BB‐L and membrane‐bound IL‐15 (mIL‐15), which is a type of IL‐15 expressed on the surface of feeder cells, is an alternative way to acquire a large number of NK cells." (PMID 38045827, 2023). "However, there are concerns about prolonged exposure to IL-15, as IL-15 transgenic mice developed leukemia with a T-cell or NK-cell phenotype." (PMID 38090585, 2023). "Finally, we used an ALL xenograft model in NSG mice to evaluate the impact of IL15 signaling for the survival and leukemia control of CAR NK cells in vivo." (PMID 35464442, 2022). "The National Cancer Institute investigated IL-15/4-1BBL-activated allo-PB-NK cell infusions following allogeneic T cell-depleted peripheral blood stem cell transplantation in 34 pediatric patients with solid tumors and leukemias (Phase I, NCT01287104, row 11)." (PMID 36348457, 2022). "Moreover, combining NK cells and exogenous IL-15 was demonstrated to enhance the immune effector cells to eradicate leukemia in post-allo-HSCT in a mouse model." (PMID 35356211, 2022).
leukemia (continued). "In a leukemia model, CD56dim NK cells activated by inflammatory cytokines IL-12, IL-15, and IL-18 will produce elevated levels of IFN-γ as part of a memory-like response when subsequently exposed to cancer cells, suggesting a possible anticancer role for this population." (PMID 36358824, 2022). "Next, we successfully constructed a CD19 specific CAR combined with IL-15-IL-15Ra fusion proteins and examined its cell viability in vitro and immunotoxicity in xenograft mouse models, which provide a candidate tool for clinical leukemia treatment." (PMID 36167591, 2022). "This study investigated whether and how IL-15 superagonist N-803 improves HPC-NK cell functionality in leukemia and OC models, and whether N-803 supports in vivo HPC-NK cell persistence and anti-OC effects." (PMID 33140189, 2021). "Furthermore, IL-15 producing DCs isolated from healthy patients and patients with leukemia (in remission) can potentiate γδ T cell cytotoxicity in vitro." (PMID 34630403, 2021). "One hundred days after the initial ip injection of 106 IL-15-secreting leukemia cells, surviving mice were re-challenged with 106 cells of the parent cell line in order to test whether long-lasting, IL-15-independent, immunity had been established." (PMID 31856922, 2019). "Large amounts of interleukin-15 (IL-15) released from normal myeloid progenitors promote leukemia control after allo-HSCT by boosting T cell alloreactivity against leukemia cells, enhancing NK expansion and instructing the generation of new memory stem T cells from naïve precursors." (PMID 31881776, 2019). "In order to determine whether IL-15 would extend survival in the 70Z/3-L leukemia mouse model over the parent line we established stable 70Z/3-L clones that produce a range of IL-15." (PMID 31856922, 2019). "Enhanced cytotoxicity of IL-15-stimulated NK cells against leukemia and rhabdomyosarcoma cell lines could be attributed to NCRs, DNAM-1 and NKG2D." (PMID 28491060, 2017). "This vaccine could be used for treatment of autoimmune diseases, leukemia or transplant rejection, scenarios where uncontrolled expression of IL-15 is related to disease’s course." (PMID 27671547, 2016). "In contrast, whole body IL-15 transgenic mice show increased inflammation and develop leukemia." (PMID 27684068, 2016). "Moreover IL-15 stimulation leads to NF-κB p65-mediated increase in Myc expression in a context of IL-15 driven leukemia." (PMID 24376448, 2013). "In terms of apoptosis inhibition, IL15 may also prevent apoptosis in leukemia cells by upregulating the expression of anti-apoptotic proteins or inhibiting the activity of pro-apoptotic proteins, allowing cancer cells to continue to survive and accumulate in the body." (PMID 40070829, 2025). "Finally, Kerbauy and colleagues successfully targeted CD30+ tumor cells with an AFM13 BiKE construct utilized for complex CD30 expressed by lymphoma or leukemia cells with CD16+CB-NK cells while testing the influence of prior NK cell activation with IL-15 in vitro and in vivo." (PMID 39339180, 2024). "Notably, two independent studies treating leukemia patients with NK cells and cytokine support by systemic IL-15 (rows 2 and 3, see also “Masonic Cancer Center”) resulted both in reduced clinical activity, possibly by promoting T cell activation and consequent acceleration of NK cell rejection." (PMID 36348457, 2022). "However, only CD123-ENG.IL15 T-cells could control leukemia progression for >25 days as judged by BLI and by flow cytometry for GFP-positive AML cells in the peripheral blood of the mice." (PMID 35615350, 2022). "Thus, high levels of IL-15 in the microenvironment may contribute to suppressing leukemia, since it can boost the effector cells." (PMID 35356211, 2022).
leukemia (continued). "The second study (NCT03774654) is exploring whether donor-derived NKT cells transduced with a vector codifying for the anti-CD19 chimeric receptor (containing CD28 as a costimulatory domain and IL-15 improving in vivo persistence) might help in patients with CD19+ lymphoma or leukemia." (PMID 31212634, 2019). "In order to determine whether the secretion of either IL-15sol or IL-15Rc by the transduced leukemia cells would elicit a protective immune response in the host, a number of clones spanning a range of IL-15 secretion levels were injected into the peritoneal cavity of B6D2F1 mice (106cells/mouse)." (PMID 31856922, 2019). "Interestingly, the form of IL-15 mattered in the context of ip-expansion of leukemia cells." (PMID 31856922, 2019). "Moreover, systemic availability of this cytokine could be detrimental as exemplified by the development of fatal leukemia in IL-15 transgenic animals." (PMID 24376448, 2013). "Our results show that novel immunocytokines with conditional IL-15 activity are capable of inducing potent NK cell responses against AML cells and identify MIC12 as promising therapeutic candidate for leukemia treatment." (PMID 40213559, 2025). "Myeloid or lymphoid progenitor cells release two key pro-inflammatory cytokines, including IL-15 and IFN-γ, which play a crucial function in eradicating leukemia cells." (PMID 39411712, 2024). "Proinflammatory cytokines, such as IL-15 and IFN-γ, that are produced by myeloid or lymphoid progenitor cells play an essential role in eliminating leukemia cells." (PMID 35356211, 2022). "In a phase I clinical trial (NCT01885897), administration of an IL-15 superagonist complex (ALT-803) significantly improved CD8+ T cell and NK cell functions in relapsed patients with leukemia post-allo-HSCT." (PMID 35356211, 2022). "There was a striking reduction in the leukemia burden in the liver, spleen, and BM of mice treated with CD123-ENG or CD123-ENG.IL15 T-cells compared to mice that had received NT or CD19-ENG.IL15 T-cells." (PMID 35615350, 2022). "Finally, we evaluated in an ALL xenotransplantation model in NOD/SCID-gamma (NSG) mice whether human CD19 CAR NK cells directed against the CD19+ blasts are relying on soluble or membrane-bound IL15 production for NK cell persistence and also in vivo leukemia control." (PMID 35464442, 2022). "In the final set of experiments, we compared the anti-leukemia activities of autologous CD123-ENG and CD123-ENG.IL15 T-cells in AML patient-derived xenograft (PDX) models." (PMID 35615350, 2022). "In each organ, there was a decreased leukemia burden and an increased frequency of human T cells in mice that had received CD123-ENG.IL15 T-cells compared to other treatment groups, mirroring the results of our peripheral blood analysis." (PMID 35615350, 2022). "It was demonstrated that NK cell lines modified for the IL-15 gene (NKL-IL15) showed greater cytolytic activity in hepatocellular carcinoma and leukemia." (PMID 34359767, 2021). "However, although the highest IL-15Rc secreting clones produce about 10 times more IL-15 than the highest IL-15sol producing clone, the overall survival of mice receiving IL-15Rc-secreting leukemia cells was significantly shorter than that of host mice injected with IL-15sol leukemia cells." (PMID 31856922, 2019). "When transferred into mice with leukemia, CD19-CAR Tscm cells were maintained with intraperitoneal injections of IL-15 and displayed improved survival over conventional CD19-CAR T cells." (PMID 30842774, 2019). "Membrane-bound IL-15 on CAR T cells mediated similar results, as demonstrated by their increased persistence and immunity against leukemia." (PMID 30842774, 2019). "Purified NK cells expanded using IL-15 exhibit upregulation of NCRs and CD69 and cytolysis of leukemia and primary ALL blasts." (PMID 28491060, 2017).
leukemia (continued). "Together with stimulation by IL-15, autocrine stimulation by PDGF-BB drives the development of this rare leukemia, and a PDGF-BB neutralizing antibody was found to inhibit growth and survival of the leukemia cells." (PMID 24359404, 2013). "Thirdly, and although IL-15 promotes the antitumor immunity mediated by NK cells and CD8+ T cells, certain tumor-promoting properties of IL-15 and/or IL-15/IL-15Rα have been noted in patients with leukemia or solid tumors." (PMID 39430751, 2024). "IL-15 improves the reconstitution of NK, NKT and CD8+ T cells following bone marrow transplantation in mice; hence, it is considered a treatment option to boost antitumor immune responses and reduce leukemia relapse." (PMID 36765626, 2023). "As leukemia development is a stochastic event that can occur at any time point, 12–16 weeks old, asymptomatic NOD.Scid.Il15−/− mice that showed increased thymic cellularity (2–10 million) were designated ‘pre-leukemic’, and cells from these mice were used for protein expression analyses." (PMID 36765626, 2023). "Similar to our findings in peripheral blood, the mice treated with CD123-ENG.IL15 T-cells also had a significantly decreased leukemia burden and a greater frequency of human T-cells (total and CD123-ENG.IL15 T-cells) in the liver, spleen, and BM compared to other treatment groups." (PMID 35615350, 2022). "The Rezvani group demonstrated that expression of IL-15 combined with an anti-CD19 CAR improved CB-derived NK cell cytotoxicity towards CD19-expressing cell lines and primary leukemia cells in vitro, and markedly extended survival in a Raji lymphoma xenograft model." (PMID 35185932, 2022). "Interestingly, when IL-2 + IL-15 and ZOL are administered to γδ T cells isolated from patients with leukemia, during 14 days of culture, they assume different phenotypic states." (PMID 34630403, 2021). "Notably, sorafenib has been shown to increase IL-15 production in mutant FLT3-ITD leukemia cells, increase IFN-γ production, and lead to metabolic reprograming of leukemia reactive T cells among relapsed patients post-allo-HCT who respond to treatment." (PMID 34976845, 2021). "In this model, we showed that treatment with UCB-NK cells in combination with supportive IL-15 potently inhibited progression of K562 cells, thereby demonstrating that UCB-NK cells are functional in vivo and have the capacity to target leukemia cells within BM upon adoptive transfer." (PMID 23755121, 2013). "While the IL-15/mammalian target of rapamycin (mTOR) and type I interferon (IFN) signaling pathways were constitutively active in NK cells purified from the leukemia murine model, these cells could not respond to stimulation with IL-15, in vitro." (PMID 38254135, 2024). "Moreover, 65% of NOD.scid mice develop spontaneous thymomas by 10 months of age, while 100% of NOD.scid mice lacking IL-15 or IL-15Rα develop spontaneous lymphoma/leukemia by 8 months of age." (PMID 36765626, 2023). "And IL-15 DCs could stimulate the proliferation of the γδ T cells by inducing the production of soluble IL-15 and IFN-γ and the contact-independent mechanism in the leukemia environment, thus promoting the antitumor activity." (PMID 33013819, 2020). "Culturing CD3-depleted PBMC for 13–20 days with IL-21 and IL-15 without additional feeder cells yields activated NK cells with a purity of >90%, which were applied in a clinical trial with 41 leukemia patients receiving infusions of donor-derived NK cells 2–3 weeks after HSCT." (PMID 28491060, 2017). "In lymphocytic leukemia, a hematologic tumor highly resistant to activated Vγ9Vδ2 T cells, IL-2 or IL-15, and TCR stimulation upregulates the expression of NK receptors NKp44, NKp46, and NKp30 on Vδ1+ T cells, allowing their acquisition of cytotoxicity against leukemia cells." (PMID 28713381, 2017).
leukemia (continued). "Taken together, our data demonstrate that Hsp90 inhibition effectively reduces the cell viability and phosphorylation of STAT3 mutated primary LGL-leukemia cells even in absence of cytokine stimulation and its effect is further increased when JAK/STAT signaling is activated with IL2 and IL15." (PMID 29228628, 2017). "To investigate whether or not plasma IL-15 correlated with NK cell activity, we stimulated elderly cohort D peripheral blood mononuclear cells in vitro with K562 leukemia cells or with low-level IL-12 and immobilized anti-NKp46 antibody, which are well-known NK cell stimuli." (PMID 29559978, 2018). "Exercise and our injected dose of IL-15 in wild-type mice were suitable to transiently reach a peak of ∼100 pg mL−1 (∼0.76 × 10−11 m) in circulation, possibly low enough to avoid the negative consequences of chronically elevated IL-15 that may trigger leukemia or pancreatic β-cell death in mice." (PMID 25902870, 2015). "Hence, the frequent development of leukemia in both NOD and C57BL/6 Scid mice lacking IL-15 suggests that IL-15 controls leukemogenesis from aberrant thymocytes escaping the impaired DNA repair process." (PMID 36765626, 2023).